ANXA1 (annexin A1)
Diseases named in the same sentence as ANXA1 in open-access papers (continued):
Sharing a sentence is not in itself a finding about the gene and the disease.
inflammation (6 papers, 2014 to 2026). Aberrant reaction of the microcirculation characterized by movement of fluid and leukocytes from the blood into extravascular tissues. "The potent anti-inflammatory effects of ANXA1 were validated in our study, although its application in spinal cord inflammation has rarely been explored." (PMID 41328334, 2026). "In conclusion, 2ME ameliorates IR-induced acute lung inflammation by upregulating the expression of endogenous AnxA1 in the lungs, alveolar epithelial cells, and neutrophils." (PMID 33796096, 2021). "AnxA1 has been shown to attenuate NF-κB activation and downstream proinflammatory cytokine production in acute lung inflammation." (PMID 33796096, 2021). "We recently reported a novel role for the exogenous AnxA1 N-terminal peptide in ameliorating IR-induced acute lung inflammation in rats by inhibiting the NF-κB pathway, and the protective effect was abrogated by BOC2 (a pan FPR antagonist)." (PMID 33796096, 2021). "Based on these findings, 2ME ameliorates IR-induced acute lung inflammation by activating AnxA1-mediated anti-inflammatory effects." (PMID 33796096, 2021). "Conclusions: 2ME ameliorates IR-induced acute lung inflammation by increasing AnxA1 expression." (PMID 33796096, 2021). "Therefore, the regulation of the NF-κB signaling pathway via the upregulation of AnxA1 might be a possible mechanism by which 2ME protects against acute lung inflammation induced by IR." (PMID 33796096, 2021). "Therefore, in this study, we investigated whether 2ME decreased IR-induced acute lung inflammation by upregulating the expression of endogenous AnxA1." (PMID 33796096, 2021). "Mice lacking AnxA1 showed increased neutrophil influx and lung inflammation in MHV-3-infected mice, and the exogenous administration of Ac2-26 decreased lung inflammation and prevented lethality provoked by SARS-CoV-2 in K18-hACE2 mice." (PMID 40956847, 2025).
neurological diseases (6 papers, 2021 to 2025). "The anti-inflammatory endogenous protein membrane-associated protein A1 (ANXA1) is an interesting target involved in the progression of many neurological diseases, modulating neuroinflammation by inhibiting leukocyte migration and pro-inflammatory mediator release." (PMID 38585359, 2024). "Annexin 1 (ANXA1) is a calcium-regulated phospholipid-binding protein which as gradually been recognized as an endogenous glucocorticoid-regulated anti-inflammatory mediator, which exerts potential therapeutic actions on the resolution of inflammation in several neurological disorders." (PMID 38790419, 2024). "Injection of human recombinant annexin A1 acutely decreased BBB permeability in young 5XFAD and Tau P301L mice, as well, further suggesting beneficial effects of annexins in neurological disease." (PMID 40411591, 2025).
neurodegenerative disease (5 papers, 2019 to 2024). A disorder of the central nervous system characterized by gradual and progressive loss of neural tissue and neurologic function. "The results showed that AS individuals had higher ANXA1 mRNA levels, which might suggest that AnxA1 is an important factor controlling the inflammatory response that triggers HTLV-1-associated neurodegenerative disease." (PMID 33632146, 2021). "Serological detection of AnxA1 in association with proviral load may provide a prognostic biomarker for HTLV-1-associated neurodegenerative disease." (PMID 33632146, 2021).
adenocarcinoma (4 papers, 2004 to 2020). A common cancer characterized by the presence of malignant glandular cells. "Down-regulation of ANXA1 seems to be exceptional in adenocarcinomas, since many clinical cases documented overexpression in adenocarcinoma of various organs, e.g. esophageal and esophagogastric junction, stomach, liver, colon, and pancreas." (PMID 25038797, 2014). "However, whether ANXA1 is oncogenic in adenocarcinoma requires a new look on the basis of our data." (PMID 25038797, 2014).
bacterial infection (4 papers, 2013 to 2024). "This suggests that the formation of 4-HNE–annexin A1 adducts, induced by viral and bacterial infection, induces an inflammatory response in the body through the PLA2-mediated pathway, as opposed to TBE." (PMID 35457192, 2022). "Although the protective effects of the AnxA1-Fpr2 system have been well studied in a variety of disease models, only a few studies have concentrated on the functions of this system in bacterial infection." (PMID 33318141, 2021). "Decreased ANXA1 in IBD patients as described here may induce an inadequate response to bacterial infection, phagocytosis signaling, and Th1-driven responses." (PMID 24130820, 2013). "Specifically, ANXA1/FPR1 interactions generally mediate wound closure, particularly in the context of bacterial infections." (PMID 39076982, 2024).
infectious disease (4 papers, 2022 to 2025). A disorder directly resulting from the presence and activity of a microbial, viral, or parasitic agent in humans. "The effectiveness of the treatment with AnxA1 peptide in our study suggests that GC therapy could be refined using a more targeted approach, particularly in infectious diseases where there is an underlying imbalance in the AnxA1 pathway." (PMID 35293862, 2022). "Annexin A1 (AnxA1) is a ubiquitous protein that plays a fundamental role in the resolution of inflammation, including in preclinical models of infectious disease." (PMID 40956847, 2025).
gastrointestinal tumor (3 papers, 2014 to 2025). "In the present study, a systematic expression profile of ANXA1 in human gastrointestinal tumors was explored by real-time RT-PCR, Western blot, immunohistochemistry, and/or immunofluoresncece." (PMID 25038797, 2014). "Therefore, a systemic investigation with standard methods was necessary to identify the ANXA1 expression profile in six gastrointestinal tumor entities." (PMID 25038797, 2014).
retinopathy (2 papers, 2023 to 2025). "Similar protective effects of ANXA1 were found in a model of retinopathy, with ANXA1 KO mice having worse outcomes." (PMID 37208759, 2023).
benign tumors (1 paper, 2020). "ANXA1 is expressed at low levels in PBMCs with benign tumors, which would affect malignant expansion." (PMID 32226026, 2020).
Head and neck tumors (1 paper, 2014).
intestinal diseases (1 paper, 2012). "The pro-resolution mediators Annexin-A1 (AnxA1) and lipoxin A4 (LXA4) exert counter-regulatory effects on leukocyte recruitment, however to date, the dual/cumulative effects of these formyl peptide receptor-2 (FPR2/ALX) agonists in the context of human intestinal diseases are unclear." (PMID 22723974, 2012).
neurodevelopmental disorder (1 paper, 2020). A behavioral and cognitive disorder with onset during the developmental period that involves impaired or aberrant development of intellectual, motor, or social functions. "Genes implicated in ASD such as Annexin 1 (ANXA1), HLA-B and CNTN6 with deletion or duplication in a spectrum of neurodevelopmental disorders and ID were upregulated in TSC1-Het and Null NPCS when compared with the WT." (PMID 31921404, 2020).
ANXA1 also shares sentences with these, for which no sentence is quoted: liver cancer (5 papers); acute lung injury (3); gastritis (3); invasive ductal carcinoma (3); larynx cancer (3); nephrotic syndrome (3); non-small cell lung carcinoma (3); pancreatic adenocarcinoma (3); Parkinson disease (3); Thrombosis (3); Addison’s disease (2); conjunctivitis (2); follicular thyroid cancer (2); Hypoxic-Ischemic Encephalopathy (2); intestinal cancer (2); joint disease (2); Kawasaki disease (2); malignant glioma (2); membranous glomerulonephritis (2); mental disorder (2); minimal change disease (2); mucinous neoplasm (2); parasitemia (2); pneumococcal infection (2); polycystic ovary syndrome (2); primary Sjögren's syndrome (2); rectal cancer (2); skin cancer (2); Stevens-Johnson syndrome (2); transient ischemic attack (2).
A further 110 diseases each share a sentence with ANXA1 in 2 papers or fewer.